PUF60 (poly(U) binding splicing factor 60)
Diseases named in the same sentence as PUF60 in open-access papers (continued):
Sharing a sentence is not in itself a finding about the gene and the disease.
bladder cancer (continued). "Intriguingly, when we investigated the PUF60 mRNA expression in primary, progressive and recurrent bladder cancer tissues of GSE128959 dataset, we found that primary or progressive bladder cancer had higher PUF60 mRNA expression than recurrent cancer." (PMID 33117697, 2020). "To further investigate the mRNA expression profile of PUF60 in different phenotypes of bladder cancer, we searched the GEO database for bladder cancer datasets that have over 90 samples as well as clinical and histopathological information of patients." (PMID 33117697, 2020). "Here, we identified poly(U) binding splicing factor 60 (PUF60) as one of the most differentially expressed genes out of 97 RNA splicing proteins between normal and bladder cancer tissues by bioinformatics analysis of TCGA bladder cancer expression data." (PMID 33117697, 2020). "Our analysis also showed that PUF60 was associated with the malignant phenotypes of bladder cancer, and our current data indicated that PUF60 promoted cell cycle progression and growth in bladder cancer cells." (PMID 33117697, 2020). "To investigate its biological functions in bladder cancer cells, we conducted in vitro cell experiment, demonstrating that knockdown of PUF60 inhibited bladder cancer cell growth and cell cycle progression, while overexpression had opposite effects." (PMID 33117697, 2020). "To elucidate the potential molecular pathways that involve PUF60 in the development and progression of bladder cancer, we conducted GO terms and KEGG enrichments analyses based on differential genes in the two groups." (PMID 33117697, 2020). "To confirm the prognostic value of PUF60 protein expression for bladder cancer patients, we next conducted Kaplan–Meier survival analysis of our tissue microarray data according to the PUF60 protein expression score." (PMID 33117697, 2020). "To corroborate that PUF60 indeed regulated bladder cancer cell growth by mediating AURKA expression, we conducted the expression rescue experiments." (PMID 33117697, 2020). "Next, we confirmed that the protein and mRNA expression of PUF60 were overexpressed in bladder cancer by analyzing our tissue microarray data and expression data from Oncomine database and GEO database." (PMID 33117697, 2020). "PUF60 knockdown significantly inhibited cell viability and colony formation capacity in bladder cancer cells, whereas AURKA overexpression reversed this inhibition effect." (PMID 33117697, 2020). "Correlation between PUF60 and clinical pathology characteristics in bladder cancer of tissue microarray data." (PMID 33117697, 2020). "In our future study, we will perform animal experiments to verify the oncogenic role of PUF60/AURKA in bladder cancer in vivo." (PMID 33117697, 2020). "However, further research is needed to explore the precise mechanisms of PUF60 in bladder cancer and its potential as a therapeutic target." (PMID 39132499, 2024). "In bladder cancer cells, the expression of PUF60 was significantly higher in tumor tissues, while high PUF60 expression was associated with malignant phenotypes and shorter survival time, overexpression of PUF60 significantly promoted cell viability and colony formation." (PMID 37632669, 2024). "Moreover, we identified aurora kinase A (AURKA) as a new downstream target of PUF60 in bladder cancer cells." (PMID 33117697, 2020). "Finally, our analysis of PUF60 mRNA expression in different molecular subtypes of bladder cancer showed that basal types had higher PUF60 mRNA expression, which was consistent with our previous analysis in TCGA dataset." (PMID 33117697, 2020). "It is worth investigating whether PUF60 is involved in other biological and functional processes of bladder cancer progression, such as migration, invasion and maintenance of stemness." (PMID 33117697, 2020).
bladder cancer (continued). "Since the roles of HNRNPF and HNRNPA2B have been investigated in bladder cancer before, while the roles of PUF60 in the development and progression of bladder cancer remains unclear, we set off to investigate the roles and functions of PUF60 in bladder cancer." (PMID 33117697, 2020). "PUF60 promoted bladder cancer cell growth by activating AURKA signaling." (PMID 33117697, 2020). "Moreover, we found PUF60 mRNA was highly expressed in advanced T stage bladder cancer in most of datasets and high grade bladder cancer also tended to have higher PUF60 mRNA expression." (PMID 33117697, 2020). "In addition, we identified AURKA as a new downstream target of PUF60 in bladder cancer cells, and also proved that PUF60 promoted bladder cancer cell growth by transcriptionally upregulating AURKA expression." (PMID 33117697, 2020). "To test whether PUF60 can regulate the expression of genes identified above, we knocked down PUF60 expression by its specific siRNAs in bladder cancer cell line 5637, and then detected the mRNA levels of 10 genes that were significantly associated with PUF60 in both TCGA and GES13507 datasets." (PMID 33117697, 2020). "This suggests that PUF60 may play an important role in bladder cancer initiation and progression." (PMID 33117697, 2020). "High expression of PUF60 and AURKA predicted poor prognosis in bladder cancer patients." (PMID 33117697, 2020). "Furthermore, we showed that there was a significant positive correlation between PUF60 and AURKA expression in bladder cancer tissues, and PUF60 and AURKA expression contributed to tumor progression and malignant phenotypes in the patients with bladder cancer." (PMID 33117697, 2020). "Correlation between PUF60/AURKA and clinical pathology characteristics in bladder cancer." (PMID 33117697, 2020). "Collectively, these results indicate that the PUF60/AURKA axis plays a key role in regulating tumorigenesis and progression of bladder cancer, and may be a potential prognostic biomarker and therapeutic target for bladder cancer patients." (PMID 33117697, 2020). "We first downloaded the mRNA expression data of normal and bladder cancer tissues from TCGA database and analyzed the mRNA expression of a total of 97 RNA splicing proteins (including SRSF family, RBM family, HNRNP family, SF3B1, PRMT5, PUF60, U2AF1, and ZRSR2) between normal and carcinoma tissues." (PMID 33117697, 2020).
Intellectual disability (4 papers, 2017 to 2025). "Most recently, syndromic intellectual disability has been described as an emerging phenotype linking variants in 2 genes, PUF60 and FAM50A, which encode spliceosomal components of the U2 snRNP and the C-stage spliceosome complexes, respectively." (PMID 37962958, 2024).
ovarian carcinoma (4 papers, 2010 to 2024). A malignant neoplasm originating from the surface ovarian epithelium. "Here, we show that PUF60 high CNV is associated with a tendency for worse survival outcomes in ovarian cancer." (PMID 39408764, 2024). "Phenotypic effects of PUF60 on ovarian cancer cell proliferation and metastasis were examined by in vitro cell proliferation assay, migration assay, and in vivo xenograft models and lung metastasis models." (PMID 37632669, 2024). "PUF60, Rad21, and LY6E are genes located on chromosome 8q24, an important locus associated with the progression of ovarian cancer and amplified region in around 14% of ovarian tumors." (PMID 39408764, 2024). "Additionally, the gene expression of LY6E is related to the expression of RAD21 and PUF60, both genes are located at chromosome 8q24, a loci frequently amplified in ovarian cancer." (PMID 39408764, 2024). "Moreover, PUF60, Rad21, and LY6E are located on chromosome 8q24, a locus often amplified and associated with the progression of ovarian cancer." (PMID 39408764, 2024). "Overall, our data validates previously known ovarian cancer genes, such as ERBB2, and also identified novel potential drivers such as MYNN, PUF60 and TPX2." (PMID 20386695, 2010).
CHARGE syndrome (3 papers, 2020 to 2026). CHARGE syndrome is a multiple congenital anomaly syndrome characterized by the variable combination of multiple anomalies, mainly Coloboma; Choanal atresia/stenosis; Cranial nerve dysfunction; Characteristic ear anomalies (known as the major 4 C's). "The PUF60 gene, as well as CHD7, is considered responsible for CHARGE syndrome, which cooperatively translocates nucleosomes to permit transcription of FGF8 by RNA pol II in neural development." (PMID 32071290, 2020). "In human disease with “ribosomopathy”, some germline variants of the FIR/PUF60 gene, generating truncated protein lacking RRM1, RRM2, P62-binding site, or RRM3/UHM, have been reported in Verheij and CHARGE syndromes." (PMID 38139171, 2023).
asthma (2 papers, 2021 to 2024). "This may suggest that patients with PUF60 deficiency have increased levels of pro-inflammatory cytokines in the absence of an infection that potentially correlates with exaggerated immunological responses during asthma, eczema, or atopic diseases." (PMID 38396730, 2024). "Many key lncRNAs implicated in ABPA and asthma were identified, respectively, i.e., AL139423.1-201, AC106028.4-201, HNRNPUL1-210, PUF60-218 and SREBF1-208." (PMID 34221710, 2021).
glioblastoma (2 papers, 2024). The most malignant astrocytic tumor (WHO grade IV). "In glioblastoma cells, PUF60 is highly expressed and correlated with poor prognosis." (PMID 37632669, 2024).
lung carcinoma (2 papers, 2020 to 2025). "Recently, PUF60 has been reported to be involved in promoting cell cycle and lung cancer progression by regulating alternative splicing of CDC25C." (PMID 40411278, 2025). "Conversely, overexpression of PUF60 was observed in several cancer types, including hepatic and lung cancer where mRNA levels seem to reflect genomic gains at 8q24.3 around the PUF60 locus and predict poor survival." (PMID 32664474, 2020).
non-small cell lung carcinoma (2 papers, 2016 to 2022). A group of at least three distinct histological types of lung cancer, including non-small cell squamous cell carcinoma, adenocarcinoma, and large cell carcinoma. "While on the other hand, PUF60 has been associated with colon and non-small cell lung cancer, and PLEC has been shown to promote the migration and invasion of neck squamous cell carcinoma." (PMID 35453681, 2022). "TFRC and KPNB1 have been previously implicated in BC, while PUF60 has been associated with colon and non-small cell lung cancer." (PMID 35453681, 2022).
renal carcinoma (2 papers, 2020 to 2022). A carcinoma arising from the epithelium of the renal parenchyma or the renal pelvis. "The identification of the specific roles of different splicing variants of PUF60 in renal cancer development and progression requires more elaborate work in our future research." (PMID 33061812, 2020). "In contrast, PUF60 overexpression in renal cancer cells stimulates telomerase reverse transcriptase (TERT) transcription due to PIF60’s binding to the TERT promoter." (PMID 36497066, 2022). "The role of PUF60/TERT in renal cancer was evaluated on cell growth in vitro and in vivo." (PMID 33061812, 2020). "While our current experimental data cannot tell whether PUF60 directly binds to TERT promoter or not, we will further determine the more detailed roles of the two proteins in regulating TERT expression and renal cancer cell growth in the future." (PMID 33061812, 2020).
renal cell carcinoma (2 papers, 2020 to 2024). "In renal cell carcinoma (RCC) cells, PUF60 promote cell growth and the patients with high expression of PUF60 had significantly shorter survival." (PMID 37632669, 2024).
ANE syndrome (1 paper, 2018). "Unlike RRM1, tested UHM substitutions in PD invariably reduced PUF60 expression, possibly through impaired folding, as shown for a RRM3 substitution in RBM28 in the ANE syndrome." (PMID 29788428, 2018).
aortic coarctation (1 paper, 2024). "This suggests a possible association between PUF60 and aortic coarctation in VRJS." (PMID 38273166, 2024).
atrial septal defect (1 paper, 2025). Interauricular communication is a congenital malformation characterized by a communication between the atrial chambers of the heart. "It is worth noting that heterozygote loss-of-function variants in PUF60 has been associated with atrial septal defects and the development of aortic arch abnormalities in multiple case reports." (PMID 40288647, 2025).
bladder urothelial carcinoma (1 paper, 2020). "We also analyzed the PUF60 mRNA expression in superficial and infiltrating bladder urothelial carcinoma of GSE120736 dataset, finding that infiltrating tissues tended to have higher PUF60 mRNA expression." (PMID 33117697, 2020).
Brain malformations (1 paper, 2024). "Brain malformations are present in a number of PUF60 variants in the literature." (PMID 38396730, 2024).
brain malignant tumor (1 paper, 2026). "Germline variant of FIR/PUF60 causes developmental disorders with brain malignant tumor is described in the literature (Patient 4 was diagnosed with pineoblastoma (WHO Grade IV), c1574T>A, pVal525Glu)." (PMID 41596295, 2026).
Cornelia de Lange syndrome (1 paper, 2024). A rare syndrome characterized by low birth weight, delayed growth, intellectual disabillity, behavioral problems, and a distinctive facial appearance (thin, arched eyebrows, low set ears, small teeth, and small nose). "Surprisingly, DNA methylation analysis revealed a pattern resembling the Cornelia de Lange syndrome (CdLS) episignature, suggesting a potential connection between PUF60 and CdLS-related genes." (PMID 38273166, 2024).
dermatomyositis (1 paper, 2016). Dermatomyositis (DM) is a type of idiopathic inflammatory myopathy characterized by evocative skin lesions and symmetrical proximal muscle weakness. "Anti-PUF60, poly(U)-binding-splicing factor, autoantibodies are reported to be detected in the sera of dermatomyositis and Sjogren's syndrome that occasionally associated with malignancies." (PMID 27756887, 2016). "A recent study reported that the detection of anti-PUF60, poly(U)-binding-splicing factor, auto-antibodies in dermatomyositis and Sjogren's syndrome, indicating it reflects the immune responses of the diseases." (PMID 27756887, 2016). "Therefore, it is natural that anti-FIR (PUF60) antibodies could be detected in the sera of cancer patients as well as in dermatomyositis and Sjogren's syndrome." (PMID 27756887, 2016).
esophageal squamous cell carcinoma (1 paper, 2018). Esophageal squamous cell carcinoma (ESCC) is a type of esophageal carcinoma (EC) that can affect any part of the esophagus, but is usually located in the upper or middle third. "Overexpression of alternative splicing of far upstream element binding protein 1 (FUBP1) interacting repressor (FIR; poly(U) binding splicing factor 60 [PUF60]) and cyclin E were detected in esophageal squamous cell carcinomas (ESCC)." (PMID 29796163, 2018).
hepatitis B virus infection (1 paper, 2020). A viral infection caused by the hepatitis B virus. "PUF60 is also involved in Hepatitis B virus infection and cancer progression." (PMID 32538777, 2020).
lung adenocarcinoma (1 paper, 2025). A carcinoma that arises from the lung and is characterized by the presence of malignant glandular epithelial cells. "We mined public datasets in which the human lung adenocarcinoma cell line PC9 was subjected to PUF60 siRNA79." (PMID 41333426, 2025).
microphthalmia (1 paper, 2021). Congenital or developmental anomaly in which the eyeballs are abnormally small. "Of the seven patients diagnosed with colobomatous microphthalmia, potentially disease-causing variants were identified in three index patients (43%) in three different genes (PUF60, BRPF1, and TGFB2)." (PMID 33418956, 2021).
pneumonia (1 paper, 2024). An acute, acute and chronic, or chronic inflammation focally or diffusely affecting the lung parenchyma, caused by an infection in one or both of the lungs (by bacteria, viruses, fungi, or mycoplasma.). "Notably, immunological phenotypes might have been overlooked in the evaluation of PUF60-related disorders, as only one case with recurrent pneumonia and upper respiratory tract infections had been reported before." (PMID 38396730, 2024).
sarcoma (1 paper, 2022). A usually aggressive malignant neoplasm of the soft tissue or bone. "We identified upregulation of Pum2, Puf60, and Fus (fused in sarcoma) known as translation repressors." (PMID 35754828, 2022).
scoliosis (1 paper, 2024). A congenital or acquired spinal deformity characterized by lateral curvature of the spine. "It’s worth noting that more than half of the reported patients with a PUF60 variant exhibit skeletal involvement, most commonly presenting as scoliosis." (PMID 38273166, 2024).
serous ovarian tumors (1 paper, 2024). "The results indicated that the expression of PUF60 in serous ovarian tumors was significantly higher than that in the normal ovarian surface epithelium." (PMID 37632669, 2024).
Sjogren syndrome (1 paper, 2016). An autoimmune disorder in which immune cells attack and destroy the glands that produce tears and saliva. "So far, the significance of anti-FIR (PUF60) antibodies remains obscure in malignant complications of dermatomyositis or Sjogren's syndrome." (PMID 27756887, 2016).
Sleep apnea (1 paper, 2024). An intermittent cessation of airflow at the mouth and nose during sleep is known as sleep apnea. "We discuss that this presentation is most likely due to the sleep apnea in this patient with generalized muscular hypotonia and does neither indicate a side effect of the treatment nor a phenotypic expansion in PUF60-related disorders." (PMID 38396730, 2024).